XBP1 (X-box binding protein 1)
Diseases named in the same sentence as XBP1 in open-access papers (continued):
Sharing a sentence is not in itself a finding about the gene and the disease.
Insulin resistance (41 papers, 2012 to 2026). Increased resistance towards insulin, that is, diminished effectiveness of insulin in reducing blood glucose levels. "The IRE1α-XBP1 signaling pathway is closely associated with insulin resistance, hepatic steatosis, and inflammation in MASH patients." (PMID 40448016, 2025). "The inositol‐requiring enzyme 1α (IRE1α) and spliced X‐box binding protein 1 (XBP‐1) pathway activation induced hepatic endoplasmic reticulum stress has been implicated in leading to insulin resistance in hypothyroid patients." (PMID 41321897, 2025). "Mice that are heterozygous for a null XBP-1 allele develop glucose intolerance, severe insulin resistance, and diabetes." (PMID 38500817, 2024). "Just as importantly, XBP1 is associated with hepatic insulin resistance via regulation of gene expression involved in hepatic glucose production." (PMID 38199991, 2024). "Deficiency in Xbp1 in mice results in insulin resistance, further supporting that the Xbp1/ER stress/HBP axis plays a pivotal role in maintaining insulin sensitivity." (PMID 37107691, 2023). "For instance, overexpression of XBP1 improves glucose metabolism in severely obese mice and in a mouse model of insulin deficiency or insulin resistance." (PMID 36341413, 2022). "In pancreatic α cells, XBP1 deficiency causes glucose intolerance and insulin resistance due to dysregulated glucagon secretion." (PMID 35269888, 2022). "Silencing of circANKRD36 targets miR-145 via XBP1 to restrain STZ-caused insulin resistance and inflammation in diabetic rats." (PMID 35184688, 2022). "Blocking the interaction between PI3K regulatory subunit and XBP1-s leads to lipid synthesis and lipid accumulation, and thus is the main cause of insulin resistance in obesity." (PMID 35269888, 2022). "XBP1 deficiency in pancreatic α-cells induces glucose intolerance and insulin resistance caused by the dysregulation of glucagon secretion." (PMID 34356855, 2021). "Deleting XBP1 increases susceptibility to intestinal inflammation or causes insulin resistance and type 2 diabetes." (PMID 34356855, 2021). "The link between ER stress and metabolism was shown in a study where mice deficient in Xbox-binding protein-1 (XBP-1), a transcription factor that modulates the ER stress response, develop insulin resistance." (PMID 25569627, 2015). "Activation of XBP1 is critical for maintaining ER function and dysregulated XBP1 expression/activity has been linked to apoptosis, cell death, and insulin resistance in diseased conditions." (PMID 25530974, 2014). "Studies indicate that mice deficient in X-box-binding protein-1 (XBP-1), a transcription factor that controls the ER stress response, develop insulin resistance." (PMID 23984075, 2013). "XBP1-deficient cells or mice are more sensitive to ER stress and insulin resistance because of PERK- and IRE1α-dependent JNK activation." (PMID 23762873, 2013). "Pancreatic β-cell-specific knockout of X-box-binding protein-1 (XBP-1), a key transcription factor in ER stress, resulted in hyperglycemia and diet-induced insulin resistance from β-cell dysfunction in mice." (PMID 39610878, 2024). "The findings were confirmed by the induced VEGFA, spliced XBP1, and insulin resistance in Class I obese individuals." (PMID 37219669, 2023). "The western blot result showed that KWZ significantly regulated the ER stress response through the PERK/eIF2α and IRE1/XBP1 signaling pathways, which are involved in glucose metabolism and insulin resistance." (PMID 34447452, 2021). "In ob/ob mice, the ER stress response in the liver is activated and Xbp1 KO mice develop insulin resistance, suggesting that ER stress is involved in obesity and insulin resistance." (PMID 28208663, 2017). "An impaired insulin signaling secondary to insulin resistance promotes a maladaptive UPR with an impaired spliced XBP1 nuclear translocation and is characterized by ATF6 and CHOP signaling in diabetic nephropathy." (PMID 26545114, 2015).
Insulin resistance (continued). "In contrast, cells with a higher level of XBP1 tolerate ER stress tolerance and show protective effects against insulin resistance." (PMID 23762873, 2013). "Previous studies have shown the involvement of the PERK/eIF2α and IRE1/XBP1 arms of the ER stress signaling pathways in hepatic steatosis and insulin resistance." (PMID 22355328, 2012). "Moreover, mice with hepatocyte-specific deletion of Xbp1 develop insulin resistance and are prone to liver injury." (PMID 36341413, 2022). "Insulin resistance was also described in Xbp1 knockout mice." (PMID 35615361, 2022). "Furthermore, in both liver and adipose tissue, ER stress-related activation of c-Jun N-terminal kinases (JNK) by deletion of an X-box binding protein 1 (XBP1) allele, aggravates insulin receptor signaling, resulting in systemic insulin resistance." (PMID 28181829, 2017). "However, we did not detect any significant changes in ATF6, p-PERK, p-IRE1, p-eIF2α., or XBP1 splicing, after one week of HFat feeding when hepatic steatosis and insulin resistance were clearly present." (PMID 22355328, 2012). "Moreover, XBP1-s inhibits the secretion of pro-inflammatory adipokines by increasing insulin signal transduction and adiponectin secretion, and by eliminating palmitate-induced adipocyte insulin resistance." (PMID 35269888, 2022). "Importantly, this constitutive UPR depends on insulin signalling, and disturbance of the INSR/P85/XBP1-mediated constitutive UPR in podocytes, for example, in type 1 diabetes (insulin deficiency) or type 2 diabetes (insulin resistance), is mechanistically linked with glomerular disease." (PMID 25754093, 2015). "Moreover, XBP-1 signaling is involved in insulin sensitivity since XBP-1+/- mice present glucose homeostasis impairment and are more susceptible to develop a diet-induced insulin resistance." (PMID 25216759, 2014). "Hyperglycemia leads to elevated glucosamine levels that are also able to induce insulin resistance and ER stress as indicated by an increased expression of the ER stress markers GRP78/BiP, XBP1 and ATF6 in both human and L6 myotubes." (PMID 35615361, 2022). "IRE1α/XBP1 activation can also inhibit the IRS1/2 signaling through inducing P300 acetyltransferase involved in glucose production, then promoting the insulin resistance in obese mice." (PMID 32397116, 2020). "XBP1 has documented involvement in glucose and lipid metabolism, providing a potential biological link with PCOS, where metabolic disturbances including dyslipidaemia and insulin resistance are noted." (PMID 38408933, 2024). "This general protein stabilization mechanism is thought to reduce ER stress, which is involved in inflammation and insulin resistance, and could explain our observations for the role of TMAO on ER stress and Xbp1 splicing in adipocytes." (PMID 28683308, 2017). "Alternatively, insulin resistance in podocytes may occur independently of other tissues and/or the INSR/PI3K/XBP1 pathway may be selectively impaired in podocytes, reflecting cell or pathway selective insulin resistance." (PMID 25754093, 2015). "After treatment with KWZ, significant activations were observed through the PERK/eIF2α and IRE1/XBP1 pathways, which were the results of GRP78 expression, indicating that KWZ might be beneficial for alleviating insulin resistance through the improving stability of the ER." (PMID 34447452, 2021). "Interestingly, DNL-induced steatosis and insulin resistance co-existed with a marked activation of the PERK/eIF2α and IRE1/XBP1 arms of the ER stress pathways while lipid oversupply was associated with the activation of JNK rather than ER stress at the early stage." (PMID 22355328, 2012).
melanoma (41 papers, 2009 to 2025). A malignant, usually aggressive tumor composed of atypical, neoplastic melanocytes. "A similar phenomenon was observed in XBP1 overexpressed melanoma cells, wherein the increasing expression of XBP1 promotes melanoma cell proliferation by activating the AKT pathway associated with MMP2 and MMP9." (PMID 34484336, 2021). "To test this, we examined the effect of 2-DG on TRAIL-R2 expression in XBP-1-deficient melanoma cell lines established by stable knockdown with shRNA by lentiviral infections." (PMID 20003459, 2009). "In parallel, the overexpression of SIRT7 in WM35 melanoma cell line resulted in up-regulation of IRE1α expression, IRE1α phosphorylation, spliced XBP1 expression, and HSPA5 expression caused by TM treatment, but marginal influence on ATF6 and phosphorylated-PERK." (PMID 36918544, 2023). "XBP1 has been implicated in the regulation of melanoma cell proliferation by activating inteleukin-6/STAT3 pathway in addition to its critical role in melanoma cell survival during ER stress." (PMID 30989459, 2019). "As triglycerides are also known to accumulate in dysfunctional melanoma-associated DC, silencing of IRE1α or XBP1 expression in these cells might also improve DC-mediated immune responses against this cancer in certain contexts." (PMID 29209327, 2017). "Although IRE1α has been implicated in cell proliferation in pancreatic islet cells and certain cancer cell lines, it remains unclear whether the IRE1α-XBP1 branch is linked to melanoma cell growth." (PMID 28222747, 2017). "In melanoma cells, XBP1 was shown to upregulate AKT phosphorylation, contributing to resistance to chemotherapeutic agents such as docetaxel and vincristine." (PMID 41372991, 2025). "In contrast, knocking down XBP1 in melanoma cells enhanced the effectiveness of anti-PD-1 immune checkpoint inhibition (ICI)." (PMID 41372991, 2025). "Comparable outcomes were observed when XBP1 was silenced in B16-OVA cells (a melanoma line expressing ovalbumin), followed by anti-PD-1 ICI." (PMID 41372991, 2025). "In melanoma, activation of the IRE1α-XBP1 pathway upregulates the expression of macrophage PD-L1 and promotes tumour immune evasion." (PMID 38297380, 2024). "The IRE1α-XBP1 arm represses the expression of the NKG2D ligand MHC class I polypeptide-related sequence A (MICA) in human melanoma cell lines undergoing ER stress." (PMID 38291473, 2024). "In melanoma, IREIα-XBP1 signalling is observed to promote M2 macrophage polarization, including the upregulation of interleukin 6 (IL-6), IL-23, and arginase 1 expression, leading to tumour immunosuppression." (PMID 38297380, 2024). "We also discovered a potential targeted regulatory relationship between LINC02202, miR‐526b‐3p and XBP1 in malignant melanoma." (PMID 38520212, 2024). "Overall, our findings suggest that LINC02202 can promote melanoma progression and inhibit T cell immune killing of melanoma cells through the miR‐526b‐3p/XBP1 pathway." (PMID 38520212, 2024). "Our study provides insights into the effects of LINC02202/XBP1 on the phenotype and function of malignant melanoma cells, offering a theoretical basis for the development of new immunotherapy strategies for this aggressive cancer." (PMID 38520212, 2024). "Our study has identified a potential targeted regulatory relationship between LINC02202, miR‐526b‐3p and XBP1 in malignant melanoma." (PMID 38520212, 2024). "In our study, we found that LINC02202 is highly expressed in melanoma and can regulate the expression of miR‐526b‐3p/XBP1/PD‐L1 axis." (PMID 38520212, 2024). "Our findings shed light on the impact of LINC02202/XBP1 on the phenotype and function of malignant melanoma cells." (PMID 38520212, 2024). "Collectively, our data proposed the model that SIRT7 deacetylated SMAD4 to trigger its ubiquitination and degradation, thereby relieved the transcriptional suppression on IRE1α to activate IRE1α-XBP1 axis and defend against ER stress in melanoma." (PMID 36918544, 2023).
melanoma (continued). "Then, we proved that SIRT7 enabled melanoma cell survival under stress, and the selective activation of the IRE1α-XBP1 branch of UPR and downstream ERK pathway driven by SIRT7 up-regulation was responsible for this effect." (PMID 36918544, 2023). "The suppressive effect of SIRT7 deficiency on melanoma progression was CD8+T cell-dependent, which was partially caused by the reduction of PD-L1 via the IRE1α-XBP1 axis." (PMID 36918544, 2023). "Taken together, our data demonstrated that SIRT7 orchestrated melanoma progression by simultaneously promoting tumor cell survival and immune evasion via the selective activation of the IRE1α-XBP1 axis." (PMID 36918544, 2023). "We treated SIRT7-overexpressed melanoma cell with IRE1α inhibitor STF083010 or the transfection with siRNA against XBP1, which displayed that the up-regulation of PD-L1 by SIRT7 was significantly suppressed at both mRNA and protein levels under ER stress." (PMID 36918544, 2023). "To ascertain the physiological relevance of these findings, we next assessed the survival of Ern1- and Xbp1-CKO mice implanted with B16.F10 melanoma cells." (PMID 32520957, 2020). "As a consequence, level of spliced XBP1 (XBP1s) mRNA was significantly diminished in all melanoma cell lines." (PMID 30989459, 2019). "Compared with normal melanocytes, six melanoma cell lines showed higher XBP1 splicing and enhanced IL-6 expression." (PMID 28222747, 2017). "The spliced form of XBP1 is frequently expressed in melanoma cell lines and in fresh melanoma isolates." (PMID 28222747, 2017). "Here, we report that the IRE1α-XBP1 branch is activated and that the spliced form of XBP1 (XBP1s) is increased in human melanoma tissues." (PMID 28222747, 2017). "Above all, IL-6 neutralization attenuated the enhanced proliferation of melanoma cells induced by the activation of the IRE1α-XBP1 branch, thus suggesting that anti-IL-6 antibody is a promising candidate for the clinical treatment of melanoma." (PMID 28222747, 2017). "Here, we demonstrated that XBP1s activated IL-6 expression by binding to its promoter in human melanoma cells, thus indicating the conservation of XBP1 behavior in controlling IL-6 expression." (PMID 28222747, 2017). "Compared with those in normal tissues, significantly enhanced protein levels of XBP1s were observed in melanoma tissues, thus indicating hyperactivation of the IRE1α-XBP1 pathway in human melanoma." (PMID 28222747, 2017). "Sixty-one pairs of melanoma specimens and corresponding normal tissues from patients were stained with XBP1." (PMID 28222747, 2017). "The mRNA and protein expression levels of XBP1s were significantly elevated in human melanoma tissues and cell lines compared with normal tissues or melanocytes, thus indicating the activation of the IRE1α-XBP1 branch in melanoma." (PMID 28222747, 2017). "UPR pathways, including the IRE1α-XBP1 branch, have been shown to have critical functions in the development of melanoma, but the exact mechanisms have been unclear." (PMID 28222747, 2017). "IL-6 expression levels were determined in both melanocytes (HEMn-MP) and melanoma cells (Mel-RMu) overexpressing the spliced form of XBP1 (XBP1s)." (PMID 28222747, 2017). "Instead, the ATF6/IRE1α/XBP-1 axis of the UPR appears to play an important role in up-regulation of TRAIL-R2 induced by 2-DG in melanoma cells." (PMID 20003459, 2009). "In this study, deficiency in XBP-1 markedly blocked up-regulation of TRAIL-R2 in melanoma cells, verifying a role of XBP-1 in 2-DG-mediated up-regulation of TRAIL-R2." (PMID 20003459, 2009). "This argues against a direct role of XBP-1 in activation of transcription of TRAIL-R2 in melanoma cells." (PMID 20003459, 2009). "We therefore envisaged that XBP-1 plays a role in up-regulation of TRAIL-R2 by 2-DG in melanoma cells." (PMID 20003459, 2009). "Instead, the XBP-1 pathway of the UPR plays an important role in 2-DG-mediated up-regulation of TRAIL-R2 in melanoma cells." (PMID 20003459, 2009).
melanoma (continued). "Isoform antagonism is especially pronounced in the context of melanoma, as SIRT1 associates with chemokine-rich CD8+-high niches and reinforces responses to PD-1 blockade, while SIRT7 triggers the IRE1α–XBP1 stress pathway to upregulate PD-L1 and promote immune evasion." (PMID 41425553, 2025). "In melanoma models, XBP1 inhibition potentiates immune checkpoint blockade efficacy, suggesting ER stress pathways may modulate therapeutic immune responses." (PMID 41209558, 2025). "Additionally, investigations on a mouse model with B16F10 melanoma have revealed an activated state of the IRE1α–XBP1 pathway in TAMs." (PMID 40035165, 2025). "Animal experiments further confirmed that LINC02202 may regulate the efficacy of immunotherapy in melanoma through the XBP1 pathway." (PMID 38520212, 2024). "LINC02202 may further regulate immune infiltration and the efficacy of immune checkpoint treatments by modulating the miR‐526b‐3p/XBP1 signalling pathway, contributing to immune evasion, proliferation and metastasis of malignant melanoma." (PMID 38520212, 2024). "It promotes melanoma progression through the miR‐526b‐3p/XBP1/PD‐L1 axis." (PMID 38520212, 2024). "Besides, we also employed immunohistochemical staining analysis in a cohort of 31 melanoma tissues, which revealed that the staining scores of XBP1 were highly correlated with those of CD8α and IFN-γ, respectively." (PMID 38291473, 2024). "In fact, selective XBP1 deletion in DC/TAM delays melanoma tumor growth." (PMID 37346037, 2023). "Mice with IRE1α- but not Xbp1-deficient macrophages showed greater survival than controls when implanted with B16.F10 melanoma cells." (PMID 32520957, 2020). "Therefore, in this study, we explored the role of shrimp miR-965 as a natural drug for melanoma therapy by disrupting the MCL-1-ER stress-XBP1 feedback loop in melanoma stem-like cells (MSLC)." (PMID 32586376, 2020). "Furthermore, inhibition of XBP1 in mouse melanoma cells also coincided with a better response to anti-PD-1 treatment." (PMID 30940817, 2019). "Hence, we sought to evaluate the role of the IRE1α-XBP1 branch in melanoma cell proliferation by performing CCK8 and BrdU assays in Mel-RMu cells." (PMID 28222747, 2017). "We then sought to determine whether IRE1α, the central mediator in the XBP1 splicing process, is involved in the regulation of IL-6 expression in melanoma." (PMID 28222747, 2017). "Compared with that in HEMn-MP and HEMn-DP cells, higher levels of XBP1u (unspliced XBP1) mRNA were spliced into XBP1s (spliced XBP1) and then translated into the active form of the protein in the melanoma cells, thus indicating constitutive activation of the IRE1α-XBP1 branch in melanoma cell lines." (PMID 28222747, 2017). "Additionally, in an inducible BRAFV600E/PTEN-driven melanoma model, a DNA vaccine that promotes XBP1 expression in endogenous DC conferred CD8+ T cell-mediated immune control of small established tumors." (PMID 29209327, 2017). "Additionally, directly suppressing XBP1 in melanoma cells enhances the effectiveness of immunotherapy when treated with antibodies targeting proteins involved in the programmed cell death 1 (PD‐1) and cytotoxic T cell lymphocyte‐associated antigen 4 (CTLA‐4) pathways." (PMID 40035165, 2025). "Therefore, apart from the regulation by NF-κB downstream of IRE1α, the expression and secretion of IL-6 and TNF-α might also be directly transcriptionally regulated by XBP1 downstream of IRE1α in melanoma undergoing ER stress." (PMID 38291473, 2024). "In addition, IRE1α-XBP1 signalling increased PD-L1 expression in TAMs and thus promoted melanoma growth, suggesting that targeting IRE1α-XBP1 signalling to TAMs combined with anti-PD-L1 therapy may be an effective strategy for the treatment of melanoma." (PMID 38297380, 2024).